RB1 (RB transcriptional corepressor 1)
Diseases named in the same sentence as RB1 in open-access papers (continued):
Sharing a sentence is not in itself a finding about the gene and the disease.
Cognitive impairment (8 papers, 2019 to 2026). Abnormal cognition is characterized by deficits in thinking, reasoning, or remembering. "We also suggest Rb1’s effects on GABAergic transmission may be correlated with its’ amelioration in PD-associated motor and cognitive deficits." (PMID 31314744, 2019). "Altogether, Rg1 and Rb1 treatment attenuated cognitive deficits induced by HLS, mitigated mitochondrial dysfunction, attenuated oxidative stress, inhibited apoptosis, increased synaptic plasticity, and restored BDNF-TrkB/PI3K-Akt signaling." (PMID 37168997, 2023). "In the present study, we address the role of Rb1 in the cognitive impairment in PD, involving spatial learning and memory." (PMID 30958793, 2019). "Pharmacological studies have indicated that Rb1 can increase hippocampal glutamatergic transmission and improve long-term potentiation and synaptic plasticity, suggesting that Rb1 may represent a potential treatment strategy for cognitive impairment." (PMID 33686024, 2021). "Although Rb1 has been demonstrated to improve spatial learning and memory by regulating hippocampal neurogenesis or inhibiting neuroinflammation and oxidative stress, little is known about the role of Rb1 in the cognitive impairment of PD." (PMID 31314744, 2019). "Whether Rb1 can improve the cognitive impairment in PD remains unknown." (PMID 30958793, 2019). "However, the question of whether Rb1 is capable of improving cognitive impairment in PD and is capable of improving hippocampal α-synuclein expression remains undetermined." (PMID 30958793, 2019). "We conclude that Rb1 mainly improves the cognitive impairment in the PD animal model, and Rb1-inducing different in vitro and in vivo α-synuclein expression pattern maybe due to the pharmacological metabolism of Rb1." (PMID 30958793, 2019). "Ginsenosides Rb1, Rd, Re, Rg1, Rg2, Rg3, Rh1, Rh2, Rh3, PF11, and NTR1, gintonin, and compound K showed potential activity in treating cognitive deficits." (PMID 32235339, 2020). "In addition, Rb1 attenuated MPTP-induced dysfunctional gait dynamic and cognitive impairment, and this neuroprotective mechanism possibly involved regulating prefrontal cortical GABAergic transmission." (PMID 31314744, 2019).
lymph node metastasis (8 papers, 1998 to 2024). "In addition, we showed a clear difference of the CTDSP1, CTDSPL and RB1 relative mRNA levels in ADC with and without lymph node metastases, but not in SCC (P≤0.05)." (PMID 31774910, 2019).
oral cancer (8 papers, 1999 to 2025). "A loss of heterozygosity and genetic alterations in RB1 have been reported in head and neck cancers, including oral cancer." (PMID 40723400, 2025). "Disruption of the RB1 and associated signaling pathways in oral cancer can therefore be exploited to improve the efficacy of current therapies and to explore novel therapeutic strategies." (PMID 35047986, 2020). "The RB1 gene is located on the long arm of chromosome 16, an area with high degree of loss of heterozygosity (LOH) in several tumor types including oral cancers." (PMID 35047986, 2020).
pineoblastoma (8 papers, 2008 to 2024). Pineoblastoma is a rare, malignant type of supratentorial primitive neuroectodermal tumor (sPNET), found mainly in children (less than 10% of cases are reported in adults), and located in the pineal region of the brain but that can metastasize along the neuroaxis. "Pineoblastoma is a rare pediatric cancer induced by germline mutations in the tumor suppressors RB1 or DICER1." (PMID 32286280, 2020). "In the context of these recent discoveries, the World Health Organization’s 2021 classification for pineoblastoma defined four molecular subtypes: miRNA processing altered 1, miRNA processing altered 2, RB1-altered, and MYC/FOXR2-activated, each with a distinct prognosis." (PMID 37444483, 2023). "Pineoblastoma was is divided into Pineoblastoma, MYC/FOXR2 activated, Pineoblastoma, RB1-altered, Pineoblastoma miRNA-1 and miRNA-2 base on a desirable diagnostic method of DNA methylation profiling." (PMID 38459438, 2024).
serous ovarian cancer (8 papers, 2012 to 2025). "Although there was only one case of clear-cell ovarian cancer, RB1 expression was higher in clear-cell ovarian cancer than that in serous ovarian cancer." (PMID 35299734, 2022). "We found that a higher expression level of RB1 was observed in endometrioid ovarian cancer than that in serous ovarian cancer." (PMID 35299734, 2022). "The protein level of RB1 in endometrioid ovarian cancer was higher compared with serous ovarian carcinoma (P <0.01)." (PMID 35299734, 2022). "Despite there was only one case of clear-cell ovarian carcinoma sample, RB1 expression was higher than that in serous ovarian carcinoma." (PMID 35299734, 2022).
urothelial carcinoma (8 papers, 2014 to 2025). A malignant neoplasm derived from the transitional epithelium of the urinary tract (urinary bladder, ureter, urethra, or renal pelvis). "The tumor suppressor gene RB1 is mutated in approximately 14% of urothelial carcinomas and is important for DNA repair." (PMID 34177933, 2021).
Infertility (7 papers, 2010 to 2022).
metastatic carcinoma (7 papers, 2017 to 2025). A carcinoma which has spread from the original site of growth to another anatomic site.
rhabdomyosarcoma (7 papers, 1989 to 2025). A rare aggressive malignant mesenchymal neoplasm arising from skeletal muscle. "Rb1 loss from an already low pRb baseline is a significant disease modifier, raising the possibility that some cases of pleomorphic rhabdomyosarcoma may in fact be Pax3:Foxo1a-expressing aRMS with Rb1 or pRb loss of function." (PMID 24274149, 2013). "Other frequently altered genes are RB1 and MYC (a well-known oncosuppressor and oncogene, respectively), NF1 (known for being often mutated in neural tumors), and PAXX (often fused with FOXO1 in alveolar rhabdomyosarcomas)." (PMID 40725011, 2025). "Surprisingly, our patient who developed rhabdomyosarcoma was negative for RB1 gene mutations, but since this testing was performed in 2006, it may have been an incomplete evaluation yielding a false-negative result." (PMID 36553426, 2022).
acute myeloid leukemia (6 papers, 2013 to 2023). Acute myeloid leukemia (AML) is a group of neoplasms arising from precursor cells committed to the myeloid cell-line differentiation. "miR-181 family members were predicted to target CTDSPL, which had previously been denoted as RBSP3 (RB1 serine phosphatase from human chromosome 3), a key downstream mediator of cell cycle progression, and has been reported to participate in acute myeloid leukemia pathogenesis." (PMID 29382357, 2018).
acute myocardial infarction (6 papers, 2016 to 2026). Necrosis of the myocardium, as a result of interruption of the blood supply to the area. "As shown by TTC staining, both individual treatments reduced the myocardial infarct area after I/R injury, and FA-Rb1 combination was more effective than Rb1 alone." (PMID 41501834, 2026). "The combination of FA and Rb1 demonstrated an enhanced cardioprotective effect, significantly reducing myocardial infarct size and the NR area in a rat model of MIRI." (PMID 41501834, 2026). "The finding that Rb1 can bind to NADH dehydrogenase in mitochondrial complex I was also verified in the mice model of acute myocardial infarction." (PMID 40682486, 2025). "Knockout of RB1 and Meis2 in adult cardiomyocytes induced cell cycle reentry and improved function of cardiac repair after myocardial infarction." (PMID 37642904, 2024). "In this study, we detected the effect of Rb1 on rat myocardial blood flow, myocardial infarct size, cardiac function, velocity of venule red blood cell, myocardial structure and apoptosis, energy metabolism and change in RhoA signaling pathway during cardiac I/R injury." (PMID 28327605, 2017). "Compared with the model group, Rb1 reduced myocardial infarction size, and caspase-3 activity, TNF-α levels, and phosphorylated p38 MAPK levels were also reduced by Rb1 pretreatment (Li and Ji, 2018)." (PMID 37547332, 2023).
cervical (6 papers, 2015 to 2024). "It is known that this oncoprotein inactivates the retinoblastoma 1 (RB1) gene by promoter methylation, which is essential in cervical tumorigenesis in humans." (PMID 26032781, 2015).
cervical tumor (6 papers, 2007 to 2021).
chordoma (6 papers, 2008 to 2025). Chordomas are rare malignant tumors arising from embryonic remnants of the notochord in axial skeleton. "Additionally, the presence of a CCNE1 deletion occurred exclusively in cluster 2 (8/10) chordomas and low-risk-group (6/10) chordomas, whereas all RB1 and CDKN2A/2B deletions occurred in cluster 1 and RB1 (5/6) deletions and CDKN2A/2B (2/3) deletions patients who were in the high-risk group." (PMID 36439461, 2022). "By merging the data, it's apparent that also RB1 (retinoblastoma) signalling plays a central role in chordoma oncogenesis." (PMID 23533570, 2013). "We conducted a phase II single-arm, open-labeled trial on palbociclib in adult patients with advanced chordomas with p16 (by immunohistochemistry) or CDKN2A (by genomic analysis) loss along with retained CDK4/6 and RB1 expression (by immunohistochemistry or RNA sequencing)." (PMID 40627883, 2025). "Additionally, the presence of a CCNE1 deletion was exclusively found in the group of chordoma patients with better outcome, whereas RB1 and CDKN2A/2B deletions were mainly found in the group of chordoma patients with worse outcome." (PMID 36439461, 2022). "In this context, it could be noted that loss of heterozygosity previously has been found for the RB1 gene in chordoma, supporting a fundamental role for the RB1-signalling pathway in chordoma oncogenesis." (PMID 18071362, 2008).
endothelial dysfunction (6 papers, 2017 to 2025). In vascular diseases, endothelial dysfunction is a systemic pathological state of the endothelium (the inner lining of blood vessels) and can be broadly defined as an imbalance between vasodilating and vasoconstricting substances produced by (or acting on) the endothelium. "Here, we investigated the beneficial effects and the underlying mechanisms of Rb1 on hypercontraction induced by high glucose (HG) and endothelial dysfunction (ED)." (PMID 37765046, 2023). "We further showed that Rb1 can effectively block RTV-induced endothelial dysfunction." (PMID 30642080, 2019). "In this study, we intend to determine whether Rb1 can interact with ERs and induce the expression of intracellular antioxidant enzyme SOD in endothelial cells to block the endothelial dysfunction caused by HAART drugs." (PMID 30642080, 2019).
Familial retinoblastoma (6 papers, 2012 to 2025). "All patients with bilateral, trilateral or familial retinoblastoma have to be considered as carriers of a heritable tumor predisposition syndrome, even if no molecular genetic analysis was performed or in the absence of detection of the oncogenic RB1 variant in blood DNA." (PMID 33919815, 2021).
Fanconi anemia (6 papers, 2020 to 2025). Fanconi anemia (FA) is a hereditary DNA repair disorder characterized by progressive pancytopenia with bone marrow failure, variable congenital malformations and predisposition to develop hematological or solid tumors. "Co-occurrence of CCNE1 amplification with RB1 loss and somatic mutations in genes involved in HR, Fanconi anemia (FA), and DNA repair was assessed using patient data from The Cancer Genome Atlas (TCGA)." (PMID 37519629, 2023). "In particular, the increased expression of genes involved in Fanconi anemia core complex and prereplication complex revealed that abnormal DNA replication is likely to codrive RBness together with the canonical cell cycle dysregulation associated to RB1 dysfunction." (PMID 40138429, 2025). "However, RB1 (25%), as well as genes involved in the HRR (e.g., RAD51 in 18.8%) and Fanconi anemia (e.g., BRCA2 in 12.5%) pathways, were also recurrently hit by HetDels." (PMID 35406559, 2022). "Other defects in homologous recombination repair genes, such as EMSY, RAD51, ATM, ATR, Fanconi anemia, BARD1, BRIP1, PALB2, RB1, NF1, CDKN2A, and the suppression of BRCA1 transcriptional activation through gene methylation, are associated with homologous recombination deficiency (HRD)." (PMID 32679669, 2020).
invasive breast carcinoma (6 papers, 2015 to 2024). A carcinoma that infiltrates the breast parenchyma. "One of the fusion splice variants involving RB1’s exon 17 and the same downstream intergenic region was detected in two other samples, a breast invasive carcinoma and an oesophageal carcinoma." (PMID 34686194, 2021). "We found that expressions of BMP-2 and CD44 were significantly upregulated, whereas expressions of RB1 and CDH1 (E-cadherin) were significantly downregulated in invasive breast cancer." (PMID 28725489, 2017).
lipoma (6 papers, 2015 to 2025). A benign, usually painless, well-circumscribed lipomatous tumor composed of adipose tissue. "We surprisingly observed rapid lipoma formation and increased marrow adipocyte size and numbers in mice with Rb1 and Pten co-deleted in osteoprogenitor cells." (PMID 26317218, 2015). "Retention of both copies of Rb1 (Osx-Cre; Ptenfl/fl) reduced the formation and delayed onset of lipoma formation even further, and only 4 of 17 mice developed them at around 9–12 months old." (PMID 26317218, 2015). "Rb immunohistochemistry or molecular tests can also identify Rb loss or RB1 gene deletion, which are not observed in conventional lipomas." (PMID 33802620, 2021).
Lung neuroendocrine tumours (6 papers, 2017 to 2025).
Merkel cell carcinoma (6 papers, 2016 to 2025). "The cell cycle pathway (CDKN2A/B, CDKN2C or RB1 genes) was also abnormal in 71% of patients (12/17) with Merkel cell carcinomas." (PMID 26981779, 2016). "RB1 gene alterations in Merkel cell cancers are associated with virus-negative disease." (PMID 26981779, 2016).
mesothelioma (6 papers, 2009 to 2022). A usually malignant and aggressive neoplasm of the mesothelium which is often associated with exposure to asbestos. "In contrast to other cancers RB1 is rarely mutated in mesothelioma but its suppressor function is inhibited due to inactivation by phosphorylation or by viruses as SV40 that recently was linked to mesothelioma oncogenesis." (PMID 19662092, 2009). "We also found previously unrecognised deletions in RB1 in 26% of cases and show sub-micromolar responses to downstream PLK1, CHEK1 and Aurora Kinase inhibitors in primary mesothelioma cells." (PMID 34580349, 2021).
oligodendroglioma (6 papers, 2003 to 2025). A well-differentiated (WHO grade II), diffusely infiltrating neuroglial tumor, typically located in the cerebral hemispheres. "RB1 and PTEN mutations are typical of GBMs, but are found infrequent in those with an oligodendroglioma component defined by machine." (PMID 24236209, 2013). "Furthermore, those GBMs classified with a low oligodendroglioma component (MOC 0) were strongly enriched in PTEN and RB1 mutations, which is more characteristic of classic GBMs with astrocytic differentiation." (PMID 24236209, 2013).